OTUB1 (OTU deubiquitinase, ubiquitin aldehyde binding 1)
Diseases named in the same sentence as OTUB1 in open-access papers (continued):
Sharing a sentence is not in itself a finding about the gene and the disease.
tumor (continued). "We investigated OTUB1 functioned as a tumor promoter in HCC through the deubiquitination of RACK1, which subsequently activated the downstream PI3K/AKT and FAK/ERK signaling pathway." (PMID 38315284, 2024). "And IHC staining of OTUB1, KI67, RACK1, p-ERK, p-AKT, and p-FAK supported that efficient OTUB1 knockdown ameliorated the hyperactivation of the oncogenic pathway, and corroborated the reduced subcutaneous tumor growth when OTUB1 silenced." (PMID 38315284, 2024). "To validate the potential key role of RACK1 in OTUB1-mediated tumor suppression, we performed the exogenous Co-IP assay first." (PMID 38315284, 2024). "To further verify the effects of OTUB1 on tumor formation in vivo, we injected Panc05.04 cells into subcutaneous tissues in nude mice after knockdown and overexpression of OTUB1, respectively." (PMID 38653740, 2024). "In vivo experiments revealed that OTUB1 knockdown inhibited tumor growth, further emphasizing its crucial role in GBM progression." (PMID 39006090, 2024). "The huh7 xenograft tumor models further showed that the stable overexpressed-OTUB1 group represented a greater tumor volume and weight than the control group." (PMID 38315284, 2024). "The ubiquitin hydrolase OTUB1 is a key regulator of ferroptosis and its expression is upregulated in tumours." (PMID 36911020, 2023). "The deubiquitinating enzyme OTUB1 enhances the sensitivity of tumor cells to erastin-induced ferroptosis by stabilizing the proteasome-dependent SLC7A11." (PMID 36369321, 2023). "Functionally, OTUB1 depletion decreases PD-L1 expression, and increases the cytotoxicity of human peripheral blood mononuclear cells against tumor cells." (PMID 37415977, 2023). "Compared with control, the OTUB1−/− group showed significantly increased tumour volume, while the tumour volume was significantly reduced in the OTUB1−/− + CCN6 group." (PMID 37608493, 2023). "Therefore, inhibiting OTUB1 may retard tumor growth or cause cell death." (PMID 38264570, 2023). "FIH has recently been reported to form tight complexes with proteins in an oxygen-dependent manner, in particular with the deubiquitinase ovarian tumor domain containing ubiquitin aldehyde binding protein 1 (OTUB1), likely via covalent bond formation." (PMID 35537551, 2022). "Pearson's correlation analysis showed a positive correlation between the expression of SNHG17 and OTUB1 in 52 PC tumor specimens." (PMID 35864871, 2022). "The expression level of OTUB1 correlates with tumor size and differentiation and predicts poor prognosis." (PMID 36339263, 2022). "In this article, we proved that OTUB1 expression up-regulation was characteristic in tumor cells of CRC cancer patients." (PMID 35354355, 2022). "And OTUB1 exhibited multi-facet promotive effects on malignant biological behaviors of CRC cancer cell including tumor cell stemness, invasion and chemo-resistance." (PMID 35354355, 2022). "OTUB1 as a deubiquitinating enzyme is a member of the ovarian tumor (OTU) family, which negatively regulates the stability and activity of ubiquitination-promoting proteins." (PMID 36339263, 2022). "OTUB1 is the founding member of the ovarian tumor (OTU) domain family of deubiquitinases (DUBs) and is expressed in various tissues in humans." (PMID 36467089, 2022). "Results demonstrated that OTUB1 protein was significantly increased in tumor tissues compared with normal tissues." (PMID 35354355, 2022). "Meanwhile, OTUB1 as de-ubiquitinase was up-regulated in several human malignancies and OTUB1 participated in tumor pathogenesis via several different routes." (PMID 35354355, 2022).
tumor (continued). "In our research, we investigated OTUB1 expression utilizing immunohistochemical (IHC) test on tumor and matched adjacent tissue of CRC patients." (PMID 35354355, 2022). "Studies have revealed the important effects of OTUB1 in many physiological and pathological processes, such as DNA repair and damage, apoptosis, inflammatory reaction, and tumor development." (PMID 34927544, 2021). "Intriguingly, we observed that EYA1 overexpression dramatically facilitated tumour growth, but OTUB1 downregulation significantly suppressed this trend." (PMID 34773364, 2021). "We further found an interesting result that the tumor volume was restrained significantly compared with OTUB1 overexpression group, when these mice were oral administrated with RO-3306 in a dose of 4 mg/kg every day." (PMID 33537306, 2020). "Of which, ovarian tumor domain-containing ubiquitin aldehyde binding protein 1 (OTUB1) is an atypical DUB in the regulation of specific ubiquitin-conjugating enzymes (E2s)." (PMID 33240928, 2020). "The expression of OTUB1 was significantly higher in the tumor tissue of CHOL, LIHC, READ, ESCA, and COAD compared with their adjacent normal tissues." (PMID 33240928, 2020). "Recent studies have shown that OTUB1 is highly expressed in invasive tumor cells and plays an important role in its proliferation and invasion." (PMID 33537306, 2020). "OTUB1 performed as a molecular indicator of poor prognosis in digestive cancers, regulated the infiltration of tumor immunocytes, and exerted a significant influence on apoptosis and autophagy." (PMID 33240928, 2020). "The relationship between OTUB1 and immune infiltrating cells was investigated through analysis of the correlations between OTUB1 and the gene marker sets of immune cells in the tumor and normal tissues with GEPIA databases." (PMID 33240928, 2020). "To find out the association of c-Maf and tumor decreases, we performed IB assays for c-Maf and Otub1 in tumor tissues." (PMID 32999280, 2020). "OTUB1-mediated deubiquitination of FOXM1 up-regulates ECT-2 to promote tumor progression in RCC, providing a new potential therapeutic target for RCC treatment." (PMID 32257108, 2020). "The expression of OTUB1 between the tumor and adjacent normal tissues was further evaluated in digestive cancers with the TIMER database." (PMID 33240928, 2020). "More molecular and animal studies are needed to verify the prospects for the clinical application of OTUB1 on tumor progress." (PMID 33240928, 2020). "The results show that the expression of OTUB1 in READ has significant correlations with tumor purity." (PMID 33240928, 2020). "To further analyze the regulatory effect of OTUB1 expression on the immune marker sets of immune cells in tumor tissues, we compared the differences of this correlation between tumor and normal tissues." (PMID 33240928, 2020). "In vivo subcutaneous xenotransplanted tumor model combined with immunohistochemistry and western blot were used to examine the tumorigenic function of OTUB1." (PMID 32257108, 2020). "It has been reported that OTUB1 plays a critical role in a variety of tumors and is strongly related to tumor proliferation, migration, and clinical prognosis." (PMID 33537306, 2020). "OTUB1 promotes tumor progression in two ways: to stabilize the expression of oncogenic genes by inhibiting the ubiquitination of target protein, and the other mode does not depend on the deproteinization manner but directly interacts with E2 ubiquitin ligase." (PMID 33537306, 2020). "The regulatory ability of OTUB1 to immune cell genes in tumor tissues and normal tissues is significantly different." (PMID 33240928, 2020). "In this study, we focus on the characteristics of OTUB1 involved in the process of cell cycle, and we investigate the specific mechanism of OTUB1 promoting tumor progression." (PMID 33537306, 2020).
tumor (continued). "The results showed that OTUB1 mRNA expression was significantly increased in the tumour tissues compared with the paired paratumorous areas (P = .010)." (PMID 30044532, 2018). "Taken together, these data strongly indicate that OTUB1 expression is essential for NSCLC tumor growth." (PMID 26881969, 2016). "Tumors resulting from cells expressing reduced levels of OTUB1, exhibited significant delay in tumor growth, with tumor sizes of only 27% as compared to controls." (PMID 25623341, 2015). "The analysis of xenograft models also demonstrates that OTUB1 can modulate tumor growth and metastatic development in vivo." (PMID 25623341, 2015). "Tumor xenograft mouse model with stable OTUB1 knockdown was used to investigate OTUB1 influence in tumor growth." (PMID 25623341, 2015). "OTUB1 expression in lymph node metastatic tumor tissues and primary CRC tissues was higher than that in adjacent normal mucosal tissues." (PMID 25431208, 2014). "High OTUB1 expression was detected in 137 tumor tissues (52.7%), and low OTUB1 expression was observed in 123 tumor samples (47.3%)." (PMID 25431208, 2014). "Compared to paired adjacent normal mucosal tissues, the expression of OTUB1 was dramatically higher in tumor tissues (P <0.01)." (PMID 25431208, 2014). "A high level of OTUB1 expression indicated a greater depth of tumor invasion, the presence of lymph node and distant metastasis." (PMID 25431208, 2014). "And OTUB1 expression in distant metastatic tumor tissues was dramatically higher than that in adjacent normal mucosal tissues or primary CRC tissues." (PMID 25431208, 2014). "Furthermore, OTUB1 promotes hypoxia-induced glycolytic reprogramming and enhances DNA damage, ultimately influencing tumor progression and metastasis through multiple molecular mechanisms." (PMID 40430059, 2025). "The regulation of OTUB1 in Tregs and CD8 T cells highlights its role in promoting an adaptive immune response, while its negative association with M2 macrophages suggests a shift away from a tumor‐promoting environment." (PMID 40600620, 2025). "Curcumol treatment significantly attenuated both protein expression and its co-localization (** p < 0.01), indicating that it disrupts OTUB1-TGFBI interactions that may be critical for tumor angiogenesis." (PMID 40430059, 2025). "To investigate the potential cooperation between OTUB1 and TGFBI in inhibiting tumor angiogenesis induced by curcumol, we employed immunofluorescence staining to assess the expression and co-localization of OTUB1 and TGFBI within the tumor tissues of nude mouse xenografts." (PMID 40430059, 2025). "Furthermore, in orthotopic HCC mouse models, the OTUB1 knockdown group displayed notably slower tumor growth." (PMID 38315284, 2024). "Therefore, OTUB1 has the potential to become a novel marker for predicting tumor progression, recurrence, and metastasis, and has broad prospects in the research and development of novel antitumor drugs." (PMID 38315284, 2024). "The results showed that the volume of tumor in elevated OTUB1 is significantly bigger compared with that in the control group, which is conversely restrained by XAV-939; while the volume of tumor in the elevated β-catenin group also is bigger than that in the control group." (PMID 39113709, 2024). "Next, we examined the potential involvement of OTUB1 in tumor metastasis in vivo." (PMID 38315284, 2024). "Moreover, AKT, FAK and ERK phosphorylation levels were higher in OTUB1-high tumor tissues as compared with OTUB1-low tumor tissues." (PMID 38315284, 2024). "Designing DUBTACs for OTUB1 could enable the reduction of prodegradative ubiquitination of tumor suppressors, leading to their stabilization." (PMID 36678835, 2023).
tumor (continued). "Therefore, we investigated the correlation among the Syk/SHP2/OTUB1/Raptor on the basis of previous data on tumor tissues with RCC." (PMID 37330581, 2023). "Collectively, these result suggest OTUB1 might suppress the immune response to host cells including tumor cells or normal cells." (PMID 38264570, 2023). "As in the case for tumor immunity, there is evidence showing OTUB1 also represses innate immunity." (PMID 38264570, 2023). "The expression of OTUB1 was notably elevated in tumor tissues with lymph node metastasis." (PMID 35864871, 2022). "Moreover, subsequent WB and qRT-PCR test provided intriguing evidences that OTUB1 overexpression also considerably enhanced stem-cell markers of CRC tumor including CD133 and CD44." (PMID 35354355, 2022). "OTUB1 overexpression significantly promoted tumor cellular migrative capacity." (PMID 35354355, 2022). "The xenograft model showed that OTUB1 depletion significantly reduced tumor growth in vivo." (PMID 36271031, 2022). "Subsequent tumor viability test provided evidences that OTUB1 shRNA1 significantly suppressed HCT116 tumor cell viability under treatment of chemo-agents, while combinatory transfection of β-Catenin overexpression vector obviously reversed the suppressive effects of shRNAs." (PMID 35354355, 2022). "Significant higher expression of OTUB1 and β-Catenin was observed in the tumor tissues." (PMID 35354355, 2022). "Moreover, WB/qRT-PCR results on CRC tumor and control normal samples showed that OTUB1 expression was notably upregulated in tumor tissues." (PMID 35354355, 2022). "In the xenograft mice model, OTUB1 depletion inhibited tumor growth, which effect could be rescued by YAP over-expression in MKN28 cells." (PMID 36271031, 2022). "The newest research indicated that CD44 played important roles that could stabilize SLC7A11 by increasing the recruitment of OTUB1 and promotes the interaction of SLC7A11 with OTUB1, thereby inhibiting the ferroptosis in tumor cells." (PMID 33869286, 2021). "Out of our expectation, Nam also downregulated Otub1 in tumor tissues excised from nude mice, suggesting that Nam might also affect Otub1 expression in vivo." (PMID 32999280, 2020). "OTUB1 is an important regulator in the level and types of tumor-infiltrating immunocytes." (PMID 33240928, 2020). "In vivo subcutaneous xenotransplanted tumor model also revealed that knockdown of OTUB1 could suppress in vivo RCC growth via down-regulation of FOXM1-mediated ECT2 expression." (PMID 32257108, 2020). "This further confirms that OTUB1 up‐regulation may contribute to the development of different tumor types harboring wt RAS." (PMID 26881969, 2016). "We propose that this modification may have important implications for the regulation of cellular metabolism by changing OTUB1 substrate targeting under conditions of hypoxia, such as those that occur during ischemia, chronic inflammation, and tumor growth." (PMID 26752685, 2016). "Through its pro-angiogenic effects, OTUB1 may further increase tumor invasiveness." (PMID 40430059, 2025).
tumor (continued). "To further explore the association between OTUB1 expression in BLCA and clinical significance, we collected and analyzed all 42 BLCA patient information, the results showed that elevated OTUB1 expression was significantly related to tumor size and poorer prognosis." (PMID 39113709, 2024). "In addition, OTUB1 affects tumor sensitivity to current therapies." (PMID 38264570, 2023). "In addition, we found that tumor incidence in OTUB1 overexpressed group was significantly faster than that in the control group, while RO-3306 restrained the tumor incidence in the OTUB1 overexpression group, indicating the critical role of OTUB1/Cyclin E1 axis in tumor formation." (PMID 33537306, 2020). "Moreover, in vivo subcutaneous xenotransplanted tumor model also indicated that knockdown of OTUB1 could suppress in vivo tumorigenic ability of RCC." (PMID 32257108, 2020). "Thus, these downstream genes might form a network centered on OTUB1 that facilitates tumor invasion and metastasis through the NF-κB and TGF-β signaling pathways." (PMID 27167337, 2016). "OTUB1 expression in the tumor stroma may also reflect a higher malignant potential of CRC." (PMID 25431208, 2014). "Untreated tumors (model group) exhibited an elevated expression of OTUB1, TGFBI, and VEGF, suggesting their active involvement in tumor angiogenesis." (PMID 40430059, 2025). "For instance, OTUB1 promoted NPC progression by regulating ferroptosis and radioresistance, while OTUD3 and OTUD4 impaired anti-tumor immune responses by stabilizing PD-L1 and CD73, respectively." (PMID 40469292, 2025). "For instance, USP22, OTUB1, and CSN5 can prevent PD‐L1 on tumor cells from being ubiquitinated and degraded, which suppresses immune cells activity in the tumor microenvironment and enables cancer cells immune escape." (PMID 38938284, 2024). "In renal cell carcinoma, OTUB1 activated ECT-2-Rho signaling through the deubiquitination of FOXM1, which accelerated tumor growth." (PMID 38315284, 2024). "Recently, we reported that phospho-OTUB1 and Raptor are overexpressed in RCC tumor tissues, and identified the positive correlation of between two proteins." (PMID 37330581, 2023). "Depletion of OTUB1 activates NK cells and CD8+ T cells, leading to increased tumor infiltration of NK cells, DCs and T cells." (PMID 37415977, 2023). "To probe into the functional roles of USP10, USP14, OTUB1, and STAMBP in HSC2 cells, we conducted assays to measure cell proliferation, in vitro invasion, and in vivo tumor growth." (PMID 37986681, 2023). "The expression of OTUB1 and UCHL5 was significantly decreased (p < 0.001) in AS, GBM, and ODG compared to non-tumor tissue, while the expression of USP3 was significantly elevated (p < 0.001)." (PMID 37892185, 2023). "Twelve of the ninety-nine DUB genes were identified as differentially expressed in MB compared to non-tumor tissue (p < 0.0001) for the GO category of DNA repair in the Swartling dataset, including USP1, OTUB1, UCHL5, USP7, and PSMD14 (aka POH1)." (PMID 37892185, 2023). "In CRC, miR-542-3p can impede tumor promotion via TUG1, and inhibit the proliferation, migration, and invasion through OTUB1, cortactin, or PI3K/AKT signaling." (PMID 35427373, 2022). "PKP3 stabilizes PD-L1 by promoting PD-L1 deubiquitination mediated by the deubiquitinase OTUB1, and PKP3 can also increase OTUB1 mRNA stability and upregulate OTUB1 expression, both of which synergistically induce tumor immunosuppression." (PMID 36139159, 2022). "Then, expressions of OTUB1, SLC7A11 and GPX4 in tumor (n=179) and normal (n=171) tissues as well as their associations with survival outcomes were evaluated." (PMID 35494004, 2022). "Our results demonstrated that OTUB1 overexpression in BCPAP triggered increased volume and weight of tumour." (PMID 34773364, 2021). "Stabilization of FOXM1 via deubiquitination by OTUB1 promotes cell proliferation and invasion of SKOV3 cells in vitro and increased tumor growth of SKOV3 mouse xenografts in vivo." (PMID 34205406, 2021).